CGAS (cyclic GMP-AMP synthase)
Diseases named in the same sentence as CGAS in open-access papers (continued):
Sharing a sentence is not in itself a finding about the gene and the disease.
lung carcinoma (continued). "Mechanistically, activation of the cGAS-STING signalling pathway is critical for TET2-mediated suppression of the tumorigenesis and metastasis of lung cancer cells." (PMID 37667220, 2023). "NEAT1 was found highly expressed in lung cancer and interacts with DNA methyltransferase DNMT1 to regulate cytotoxic T cell infiltration in lung cancer by inhibiting the cGAS/STING pathway." (PMID 37144123, 2023). "Two cohorts were evaluated comprising 721 non–small cell lung cancer (NSCLC) patients and 55 NSCLC cell lines for STING and cyclic GMP‐AMP synthase (cGAS) expression using immunohistochemistry." (PMID 35099823, 2022). "Thus, we developed a microfluidic model that could support culture and formation of vascularized KL lung cancer spheroids, with the specific goal of studying how tumor cell dsDNA sensing via cGAS-STING might modulate innate immune signaling in this more physiologically relevant milieu." (PMID 33013881, 2020). "This comprehensive review endeavors to elucidate the molecular and genetic structures of NLRC3, its role within the immune system, and its interaction with the cGAS-STING pathway, with a particular emphasis on its potential applications in lung cancer immunotherapy." (PMID 39439455, 2024). "Therefore, the cGAS-STING pathway plays a complex and critical role in lung cancer progression and immune evasion." (PMID 39439455, 2024). "Gezhe found that aerobic endurance exercise activated the cGAS-STING signaling pathway while HIIT did not in lung cancer tissue, which was contrary to our findings." (PMID 37762143, 2023). "However, cGAS and STING expression is significantly reduced in human SCLC as compared to normal lung and other lung cancers leading to a marked impairment of the cGAS/STING pathway." (PMID 36918931, 2023). "cGAS expression showed no expression difference among lung cancer types, while TBK1 and IRF3 showed a low downregulation only in SCLC tumour samples." (PMID 35794238, 2022). "Hence, cGAS-STING signaling plays a crucial role in the immune environment of different tumor microenvironments, including the lung cancer one." (PMID 33643304, 2020). "This review comprehensively discusses the activation mechanisms of three major innate immune pathways in lung cancer-cGAS-STING, TLR, and RLR signaling-the tumor-mediated negative regulatory mechanisms that suppress them, and their impact on the tumor immune microenvironment." (PMID 42199421, 2026). "Additionally, ROP16 can polyubiquitinate STING, inhibiting the cGAS-STING signaling pathway, reducing inflammatory cytokine secretion, and inhibiting STAT1 and NF-κB pathways, ultimately preventing brain metastasis of breast and lung cancer." (PMID 40684184, 2025). "Consequently, the cGAS-STING pathway assumes a complex and critical role in lung cancer progression and immune evasion, necessitating further investigation to fully elucidate its therapeutic potential and address the challenges associated with targeting it for lung cancer therapy." (PMID 39439455, 2024). "Using KRAS-LKB1 mutant lung cancer as a model, we demonstrate that tumor cell cGAS-STING not only regulates chemokine-mediated immune cell recruitment, but also directly influences the gatekeeper function of tumor vasculature via extracellular transfer of 2′3′-cGAMP." (PMID 33013881, 2020).
lung carcinoma (continued). "Thus, by engaging a tumor non-autonomous mechanism involving cGAS-STING and innate immunity, the combination of osimertinib and anti-HER3 antibodies could improve the limited therapeutic and stratification options for advanced stage lung cancer patients with mutant EGFR." (PMID 35347108, 2022).
Obesity (54 papers, 2018 to 2026). Accumulation of substantial excess body fat. "Firstly, Although our data support a model whereby Nrf2 deficiency alleviates obesity-associated inflammation by improving mitochondrial health and suppressing the cGAS-STING pathway, future studies must directly visualise and quantify mtDNA release." (PMID 41601924, 2026). "Recent studies have identified major AS risk factors—aging, smoking, obesity, hypertension, dyslipidemia, and diabetes —which promote disease progression through activation of the cGAS-STING pathway." (PMID 40351606, 2025). "Obesity causes activation of the cyclic GMP-AMP synthase (cGAS)/STING pathway, resulting in the development of hippocampal inflammation." (PMID 37860765, 2023). "Cytoplasmic mitoDNA-induced cGAS-STING activation plays a critical role in the pathogenesis of obesity-associated diabetic cardiomyopathy." (PMID 37537600, 2023). "Owing to the association between FFAs and severe obesity, these results at least partially support our results regarding the role of FAs in cGAS‐mediated anticancer immunity." (PMID 36950761, 2023). "Because of this, the cGAS-cGAMP-STING signaling pathway appears to be involved in obesity-associated adipose inflammation, as well as NAFLD phenotype." (PMID 34943809, 2021). "Obesity-induced mtDNA was reported to be associated with inflammatory responses due to the activation of the cGAS-cGAMP-STING pathway." (PMID 32249844, 2020). "While risk factors such as aging, obesity, smoking, hypertension, and diabetes are known to exacerbate AS, emerging evidence suggests that these factors may also enhance cGAS-STING pathway, which amplifies inflammatory responses." (PMID 40351606, 2025). "Overall, our findings suggest that cGAS/STING signaling may play a sex-specific role in susceptibility to HFD-induced obesity, microglial activation, and cognitive responses." (PMID 37206668, 2023). "Targeting the cGAS-cGAMP-STING pathway in adipose tissue may provide another approach to ameliorate obesity-associated inflammation and metabolic disorders by downregulating the levels of proinflammatory genes, including IFN-α." (PMID 36552805, 2022). "Evidence accumulated over the past years reveals that activation of the cGAS‒STING pathway by self-DNA may contribute to obesity-induced sterile inflammation and associated metabolic dysfunctions (Bai and Liu, 2019)." (PMID 34665236, 2021). "Increasing DsbA-L expression or suppressing cGAS–STING signaling in adipose tissue may be a potential therapeutic approach to ameliorate obesity-induced chronic inflammation and its associated metabolic diseases." (PMID 32444826, 2020). "Hence, cGAS-STING inhibition has the potential to decrease obesity-associated inflammation, type 2 diabetes mellitus (T2DM), NASH/NAFLD, defective wound healing, and angiogenesis." (PMID 33643304, 2020). "Targeting adipose cGAS-STING pathway may thus be a potential therapeutic strategy to counteract overnutrition-induced obesity and its associated metabolic diseases." (PMID 32444826, 2020). "Therefore, targeting the adipose cGAS–STING signaling pathway may be a potential treatment strategy for obesity and related metabolic diseases caused by excess nutrition." (PMID 38525112, 2024). "This suggests that obesity may downregulate mitochondrial DsbA-L expression and function, causing mitochondrial impairment and resulting in the mtDNA cytosol leak, activation of cGAS–STING pathway-mediated inflammatory responses, and eventually IR and MetS." (PMID 34906241, 2021). "Our study uncovers a link of mitochondrial dysfunction-derived immune response to thermogenesis and energy expenditure in adipose tissue, suggesting the cGAS–STING pathway may be an effective therapeutic target for the treatment of obesity and its associated diseases." (PMID 32444826, 2020).
Obesity (continued). "Specific Nrf2 knockdown in adipose tissue attenuates obesity-induced adipose tissue inflammation by inhibiting the cGAS-STING pathway, providing a novel therapeutic strategy targeting the adipose-specific antioxidant-inflammatory regulatory network." (PMID 41601924, 2026). "Oxidative stress in adipocytes during obesity induces mitochondrial membrane lipid peroxidation, leading to the leakage of mtDNA into the cytoplasm, which activates the cGAS-STING pathway." (PMID 41601924, 2026). "We further confirmed at the protein level that obesity activates the cGAS‐STING pathway and its downstream targets, whereas DPR suppresses this activation in the hearts of obese mice." (PMID 41549510, 2026). "Dietary protein restriction protects the aging heart in the context of obesity by limiting mitochondrial DNA leakage and suppressing cGAS–STING‐driven inflammation." (PMID 41549510, 2026). "Previous studies highlight the crucial role that cytosolic mtDNA-induced cGAS-STING activation plays in the pathophysiology of obesity." (PMID 39679260, 2024). "In the context of obesity-induced cardiac dysfunction, overactivation of the cGAS-STING pathway leads to increased inflammation and impaired mitochondrial autophagy." (PMID 39669992, 2024). "In summary, overnutrition, cytokines and cytosolic DNA can activate broad-spectrum cGAS-STING signalling in different cell types of adipose tissue under conditions of obesity, thereby contributing to inflammation and influencing energy metabolism." (PMID 38164186, 2024). "The cGAS-STING-mediated inflammatory response is found not only in immune cells under conditions of obesity but also in some metabolic cells." (PMID 38164186, 2024). "Further studies can be focused on the interactive pattern of JNK (or other kinases in the MAPK group) with cGAS-STING in patients with obesity." (PMID 38164186, 2024). "Recently, aberrant signalling of the cGAS-STING axis has been recognised to be closely associated with several sterile inflammatory diseases (e.g. non-alcoholic fatty liver disease, obesity)." (PMID 39301315, 2024). "Inflammation caused by cytoplasmic mtDNA via activation of the cGAS-STING pathway is a factor in aging and metabolic syndrome associated with obesity." (PMID 38813101, 2024). "Studies have proved that the 293Q mutation of the STING allele, which causes damage to the immune function of cGAS-STING, can weaken the SASP associated with obesity." (PMID 38312740, 2024). "Free fatty acids trigger endothelial inflammation through the STING–IRF3 axis in adipose tissue in diet-induced obesity in vivo and inhibit endothelial angiogenesis through cGAS-STING-IRF3 signalling in vitro." (PMID 38129863, 2023). "Activation of cGAS/STING by cytosolic mtDNA mediates lipotoxicity-induced podocyte injury in DKD or diet-induced obesity." (PMID 37354378, 2023). "In this study, we observed the presence of mitochondrial damage, cytosolic mtDNA, and activation of the cGAS-STING signaling pathway in cardiomyocytes from an obesity-related DCM mouse model." (PMID 35235096, 2023). "Recently, a growing body of evidence has demonstrated that the cGAS-STING system plays a central role in numerous diseases such as obesity, nonalcoholic fatty liver disease (NAFLD), and acute kidney injury." (PMID 35235096, 2023). "Adipose tissue levels of STING1 and CGAS were unaffected by obesity status, albeit plasma STING1 level was moderately increased with increasing BMI z-score." (PMID 37830559, 2023). "Obesity suppresses the expression of DsbA-L and destabilizes mtDNA, promoting its release and activation of the cGAS-STING pathway, which increases the expression of TBK1, NF-kB, P65, and IRF3 genes." (PMID 37569389, 2023). "The second was used to understand the role of cGAS/STING under clinically relevant conditions of obesity and prediabetes and characterize the resulting metabolic, inflammatory, and cognitive responses." (PMID 37206668, 2023).
Obesity (continued). "Obesity leads to the release of mtDNA to the cytoplasm, which leads to an inflammatory response by activating the cGAS–STING signaling pathway." (PMID 35536585, 2022). "HFD-induced pro-inflammatory responses through upregulated cGAS/STING signaling in peripheral tissues has been proposed as a potential pathological mechanism in obesity and prediabetes/diabetes." (PMID 36248795, 2022). "The deleterious role of cGAS/STING inflammatory signaling in obesity and metabolic dysfunction is well established in the periphery, particularly in adipose tissue)." (PMID 36248795, 2022). "Obesity leads to the release of mtDNA from adipose tissue cells to the cytoplasm, which leads to inflammatory responses through the activation of the cGAS–STING signaling pathway, and then induces insulin resistance and diabetes." (PMID 35536585, 2022). "In conclusion, it elucidated the critical role of cytosolic mtDNA-induced cGAS-STING activation in the pathogenesis of obesity-related DCM and provided preclinical validation as a new potential therapeutic strategy for the treatment of DCM." (PMID 36072862, 2022). "A study demonstrated that obesity induced mtDNA release and activated the cGAS-cGAMP-STING pathway, resulting in chronic inflammation in adipose tissues." (PMID 36552805, 2022). "The cGAS–STING–IRF3 pathway plays a role in metabolic stress-induced endothelial inflammation in obesity." (PMID 36139069, 2022). "While there is ample evidence to suggest a role for cGAS/STING in obesity and prediabetes/diabetes in the periphery, the role of cGAS/STING in the brain is less clear." (PMID 36248795, 2022). "In contrast, DsbA-L overexpression protects against mtDNA leakage induced by obesity and consequently against the cGAS–STING signaling pathway." (PMID 34906241, 2021). "In this review, we summarize current understanding of the cGAS‒STING pathway in several metabolic diseases such as obesity, insulin resistance, alcoholic and nonalcoholic fatty liver diseases, as well as acute kidney injury and chronic kidney disease." (PMID 34665236, 2021). "Obesity promotes mtDNA release into the cytosol of adipocytes, which leads to cGAS-STING-mediated inflammation." (PMID 34659260, 2021). "Obesity-related increase in free fatty acid induces mitochondrial damage and mtDNA release, which activates the cGAS/STING pathway leading to IRF3-dependent upregulation of ICAM-1 expression and endothelial inflammation." (PMID 34659260, 2021). "Taken together, these results suggest that abnormal activation of cGAS‒STING‒IFN signaling in adipose tissue contributes to obesity-induced insulin resistance and metabolic dysfunction." (PMID 34665236, 2021). "It was recently reported that obesity induces the accumulation of mtDNA directly in adipocytes, which ultimately activates the cGAS-STING pathway." (PMID 33574823, 2020). "The cGAS-STING signaling is also involved in high-fat diet-induced obesity as deleting STING in mice protects them." (PMID 33643304, 2020). "In summary, this study clarifies the mechanism by which Nrf2 in adipose tissue regulates obesity and associated metabolic inflammation via the non-canonical cGAS–STING pathway." (PMID 41601924, 2026). "This suggests that by blocking the activation of the cGAS-cGAMP-STING pathway caused by mtDNA release, DsbA-L, a crucial regulator of mitochondrial integrity, shielded mice from inflammation and metabolic failure caused by obesity." (PMID 39114669, 2024). "This further implies that obesity-induced chronic inflammation may be ameliorated by focusing on the cGAS-cGAMP-STING axis in adipose tissue." (PMID 39114669, 2024). "In the obesity‐related diabetic cardiomyopathy mouse model, lipotoxicity‐induced mtDNA release was observed to induce cardiac cell death and fibrosis via activation of the cGAS–STING signaling pathway and subsequent inflammation." (PMID 38525112, 2024).
Obesity (continued). "HFD-induced cGAS/STING signaling promotes pro-inflammatory responses that may contribute to the pathogenesis of obesity and prediabetes/diabetes." (PMID 37206668, 2023). "In conclusion, our study elucidated the critical role of cytosolic mtDNA-induced cGAS-STING activation in the pathogenesis of obesity-related DCM and provided preclinical validation for using a STING inhibitor as a new potential therapeutic strategy for the treatment of DCM." (PMID 35235096, 2023). "Given that the TLR4, TLR9 and cGAS-STING signaling pathway is activated under obesity conditions in NAFLD patients and mouse models, it is tempting to speculate that TLRs and cGAS-STING contribute to increased inflammation in the progression of NAFLD to NASH." (PMID 37020586, 2023). "Therefore, our goal was to create and characterize a model to better explore the role of cGAS/STING specific signaling in the CNS during obesity and prediabetes." (PMID 37206668, 2023). "Therefore, as HFD induced early obesity, glucose intolerance, and microglial activation in female cGAS-/- mice fed HFD, we expected to observe impaired cognitive response in females." (PMID 37206668, 2023). "Therefore, our goal was to establish a murine model to specifically target the cGAS/STING pathway to study obesity- and prediabetes-induced cognitive impairment." (PMID 37206668, 2023). "In addition, Bai’s research group investigated the mechanism of activation of the cGAS-cGAMP-STING signaling pathway in obesity that leads to insulin resistance, sterile inflammation, and energy dysregulation." (PMID 37569389, 2023). "Additionally, our recent work shows dysregulation of hippocampal cGAS/STING during early obesity and prediabetes and suggests a critical role for microglia in the process." (PMID 37206668, 2023). "Taken together, these results suggest that abnormal activation of cGAS–STING signaling may lead to obesity-induced insulin resistance and metabolic disorders, as well as the occurrence of NASH." (PMID 35536585, 2022). "The activation of the cGAS–STING pathway by DNA may lead to obesity and further promote metabolic disorders in the body." (PMID 35536585, 2022). "The prevailing hypothesis is that the obesity leads to a mitochondrial stress and a subsequent mtDNA release into the cytoplasm, which activates cGAS-STING pathway." (PMID 34467853, 2021). "This study presents the cGAS-STING pathway as a potential target for anti-obesity therapeutics." (PMID 32444826, 2020). "More recently, obesity induced either by HFD or genetically by the deficiency of the leptin receptor (db/db mice) was shown to promote the accumulation of mtDNA and the activation of the cGAS pathway in adipocytes." (PMID 33574823, 2020). "Since current smoking triggers DNA damage that, similar to obesity, may result in the release of DNA into the cytoplasm, we hypothesized that the cGAS/STING pathway can modify the phenotype of aging also in obese subjects." (PMID 32190093, 2020). "Furthermore, the DsbA-L gene was shown to suppress obesity-induced inflammation and insulin resistance by inactivating the cGAS-cGAMP-STING pathway." (PMID 32249844, 2020). "However, the regulatory roles of NRF2 and the cGAS-STING pathway in obesity-related metabolic disorders remain unclear." (PMID 41601924, 2026). "However, it remains unclear whether Nrf2, as a core antioxidant regulator, influences obesity-induced inflammation and metabolic disorders in adipose tissue by modulating the cGAS–STING pathway." (PMID 41601924, 2026). "Activation of the cGAS‐STING pathway and its downstream effector, IFN‐γ, was significantly elevated during obesity but was normalized by DPR." (PMID 41549510, 2026). "On the other hand, inflammatory signaling mediated by cGAS‐STING in adipose tissue suppresses thermogenesis, contributing to obesity progression." (PMID 39158380, 2025). "This mtDNA triggers cGAS-STING activation in adipose tissue and macrophages during obesity, thereby exacerbating chronic sterile inflammation." (PMID 40351606, 2025).